LINC01550 (long independently transcribed non-coding RNA 1550)
Synonyms: C14orf64
Gene: Long non-coding RNA gene on chromosome 14 (97,924,637 to 97,987,918, reverse strand). Ensembl gene ENSG00000246223.
Diseases named in the same sentence as LINC01550 in open-access papers:
LINC01550 is named in the same sentence as 5 diseases in open-access papers, as found by Europe PMC text mining. Sharing a sentence is not in itself a finding about the gene and the disease. The quoted sentences say what the papers report.
melanoma (3 papers, 2022 to 2023). A malignant, usually aggressive tumor composed of atypical, neoplastic melanocytes. "By contrast, elevation of LINC01550 induces apoptosis and cell cycle arrest leading to a better outcome of patients with malignant melanoma." (PMID 36376973, 2022).
cancer (1 paper, 2022). A tumor composed of atypical neoplastic, often pleomorphic cells that invade other tissues. "Currently, four FRlncRNAs (LINC01615, LINC01550, EPB41L4A-DT, and LINC00944) have been reported to be related to cancer development." (PMID 35350243, 2022).
tumor (1 paper, 2022). "The expression levels of LINC00460, LINC00944, LINC01550, and EPB41L4A-DT differed across the four stages, suggesting that four FRlncRNAs were closely related to the tumor stage." (PMID 35350243, 2022).
LINC01550 also shares sentences with these, for which no sentence is quoted: alcoholic cirrhosis (1 paper); lung adenocarcinoma (1).